BRCA1 (BRCA1 DNA repair associated)
Diseases named in the same sentence as BRCA1 in open-access papers (continued):
Sharing a sentence is not in itself a finding about the gene and the disease.
ovarian carcinoma (3,346 papers, 1995 to 2026). A malignant neoplasm originating from the surface ovarian epithelium. "ctDNA sequencing analysis can identify potential BRCA1/2 reversal mutations in ovarian cancer patients, facilitating the screening of patients who are suitable for PARP inhibitor therapy." (PMID 41602395, 2026). "Large genomic rearrangements (LGRs), occurring as copy number alterations (CNAs), represent a clinically relevant class of pathogenic or likely pathogenic variants (P LPVs) in BRCA1/2 (BRCA) genes in ovarian cancer (OC)." (PMID 42123545, 2026). "Using non-small cell lung cancer and BRCA1-deficient breast and ovarian cancer models, we demonstrate that RPA is critical for sustaining replication fork speed under normal conditions and for facilitating replication restart following fork stalling." (PMID 42049240, 2026). "Interventions that target decisional conflict are needed to increase the uptake of RRSO which will result in a reduction of the risk of ovarian cancer in women with BRCA1 or BRCA2 PV." (PMID 41547865, 2026). "This retrospective study aimed to assess the positive rate of endometrial cytology and compare to cervical cytology in ovarian cancer patients with patients with BRCA1/2 germline pathogenic variants (gPV)." (PMID 41692918, 2026). "The prevalence of BRCA1/2 mutations was enriched in our cohort as compared to the prevalence of BRCA1/2 mutations among all women with ovarian cancer (15 %)." (PMID 41567614, 2026). "BRCA1/2 germline mutations are the most significant genetic risk factors for epithelial ovarian cancer, occurring in 6–15% of women diagnosed with this disease." (PMID 41602395, 2026). "Carriers with a germline mutation in the BRCA1 gene have an increased lifetime risk of breast and ovarian cancer and other malignancies." (PMID 41896346, 2026). "While lifestyle factors contribute to rising incidence, 5–14% of cases result from pathogenic variants in core susceptibility genes such as BRCA1, which also increases ovarian cancer risk and, in men, prostate cancer risk." (PMID 41814353, 2026). "The ovarian cancer cumulative risk to age 80 years is considerably higher in women with a pathogenic BRCA1 variant compared to those with a pathogenic BRCA2 variant (BRCA1: 44%, BRCA2: 17%)." (PMID 41528496, 2026). "Dysbiosis, characterized by a decline in Lactobacillus and increased microbial diversity, has been associated with ovarian cancer and risk factors such as BRCA1 mutations." (PMID 41486167, 2026). "The article presents the current state of knowledge on genetic modifiers of ovarian cancer risk in women carrying pathogenic variants (PVs) in the BRCA1 and BRCA2 genes, which are major contributors to hereditary susceptibility to this malignancy." (PMID 41681824, 2026). "In summary, we show that SETD1A loss renders ATM-deficient and BRCA1-mutated breast, lung, and ovarian cancer cells resistant to PARPi by restoring HR, and that this is partly driven by defective EME1 transcription." (PMID 39994444, 2025). "This underscores the importance of PARPis, such as talazoparib and olaparib, both potent inducers of PARP trapping, in the clinical treatment of HR-deficient breast and ovarian cancer caused by BRCA1/2 mutations (BRCAm)." (PMID 40460005, 2025). "Further recontact regarding risk-reducing bilateral salpingo-oophorectomy (RRBSO) should occur at different ages depending on gene-specific ovarian cancer risk: 35–40 years (BRCA1) and 40–45 years (BRCA2)." (PMID 41159931, 2025). "Studies indicate that women with a family history of ovarian cancer have a significantly higher risk of developing the disease, with pathogenic germline variants in the BRCA1/2 genes accounting for a substantial proportion of cases." (PMID 40188947, 2025). "This is clearly observed in BRCA1-deficient breast and ovarian cancers, where the loss of BRCA1 function results in increased R-loop formation, DNA damage, and chromosomal rearrangements, accelerating tumorigenesis." (PMID 40271193, 2025).
ovarian carcinoma (continued). "Another study revealed higher HE4 levels in wild-type ovarian cancer patients compared to those with BRCA1/2 mutations, correlating with micronodular carcinomatosis and a poor prognosis." (PMID 39878156, 2025). "For the ICER of the FH-based strategy, the variable with the greatest impact was the ovarian cancer risk for BRCA1/2 carriers (p15)." (PMID 40567951, 2025). "In ovarian cancer patients, the BRCA1 mutation has shown a 4-fold greater risk for brain metastases compared to the BRCA1 wildtype and has led to an 8-month earlier diagnosis of brain metastasis." (PMID 40371388, 2025). "Given the proven impact of BRCA1/2 germline mutations on the incidence of breast and ovarian cancer, integrating BRCA1/2 mutation testing into screening programs has become imperative." (PMID 40567951, 2025). "People with a family history of breast or ovarian cancer are often advised to undergo genetic testing for BRCA1 mutations so preventive measures can be implemented and early detection occurs." (PMID 40141415, 2025). "The HRD status is predominantly associated with BRCA1/2 mutations in ovarian cancer, though some studies consider this parameter separately for the development of AI tools." (PMID 41226862, 2025). "BRCA1-deficient ovarian cancers exhibit chromatin instability, leading to the release of dsDNA into the cytoplasm, which activates the STING pathway." (PMID 39949780, 2025). "Reversion of the BRCA1/2 mutation can lead to clinical PARPi resistance in BRCA–germline-mutated ovarian cancer." (PMID 41228382, 2025). "In the present article, we identified upregulated genes expressed in the surfaceome of breast and ovarian cancers with mutations in the BRCA1 and BRCA2 genes." (PMID 40647506, 2025). "BRCA1/2 mutations are among the most important and extensively studied biomarkers in ovarian cancer." (PMID 40395324, 2025). "Patients carrying BRCA1/2 mutations have an increased risk of ovarian cancer, necessitating close monitoring and follow-up of the ovaries and uterus during the follow-up process." (PMID 40338860, 2025). "Earlier RRSO among BRCA1 carriers suggests that genetic counseling effectively conveys their higher and earlier ovarian cancer risk." (PMID 40862027, 2025). "Mutations in BRCA1 are most famously linked to hereditary breast and ovarian cancers, significantly increasing the risk of developing these cancers." (PMID 39996991, 2025). "BRCA1/2 carriers, although more widely associated with breast and ovarian cancers, have also been shown to carry elevated risks for gastrointestinal primaries." (PMID 41303799, 2025). "BRCA-1 and -2 mutations, in the mother or sisters, increase the risk for breast (RR = 6.3) and ovarian cancer (RR = 5.3) in young women, but, within mutation-positive families, the risk of BC increases 26.6-fold." (PMID 40282509, 2025). "As reported, mutations in specific genes lead to an increase in the development of some types of tumours, as the risk of breast cancer for BRCA1/2 mutation carriers is 60–80%, while that of ovarian cancer is 20–45%." (PMID 41335382, 2025). "Most studies focus on understanding differences in transcriptome profiles of ovarian cancer patients bearing variants in BRCA1 or BRCA2." (PMID 41463479, 2025). "Models like BRCAPRO and BOADICEA are specifically tailored for individuals with a family history of breast and ovarian cancers, providing valuable insights into genetic mutations, including BRCA1 and BRCA2, as primary risk factors." (PMID 40599862, 2025). "The emergence of PARPis as a therapeutic strategy has revolutionized the treatment landscape for BRCA1/2-mutated breast and ovarian cancers." (PMID 40460005, 2025). "Germline mutations of BRCA1/2 were found in around 7% of breast and pancreatic cancers, and in 15% of ovarian cancers, but only in 1.5% of prostate cancers." (PMID 39985088, 2025).
ovarian carcinoma (continued). "Only two patients discontinued treatment with an aLHRH following ovarian adnexectomy: one due to synchronous ovarian carcinoma, and one as prophylaxis due to a pathogenic BRCA1/2 mutation." (PMID 40862790, 2025). "BRCA1/2-associated breast and ovarian carcinomas are often regarded as a single entity, assuming that BRCA1 and BRCA2 genes are almost equivalent with regard to their clinical significance." (PMID 40547808, 2025). "We have previously established an in vitro model of PARPi-resistant ovarian cancer by long-term exposure of BRCA1-deficient UWB1.289 ovarian cancer cell lines to olaparib." (PMID 39915607, 2025). "The discovery of BRCA1/2 mutations as potent drivers of tumorigenesis revolutionized breast and ovarian cancer treatment, and prostate cancer soon followed suit." (PMID 40427518, 2025). "BRCA1 PV carriers had a significantly higher risk of developing second breast or ovarian cancer than BRCA2 or WT carriers (p = 0.010)." (PMID 40422528, 2025). "Germline BRCA1/2 variant testing was performed in only one case (case d) among the 30 cases of recurrent ovarian cancer that achieved a 4-year DFS." (PMID 41008914, 2025). "In parallel, PARP inhibitors have transformed the management of epithelial ovarian cancer, particularly in patients with BRCA1/2 mutations or broader homologous recombination deficiency (HRD)." (PMID 41541937, 2025). "Olaparib demonstrated an improvement in progression-free survival in patients with platinum-sensitive, relapsed ovarian cancer and BRCA1/2 mutations." (PMID 40243501, 2025). "The use of oral contraceptives for over 1 year has been found to significantly reduce the risk of ovarian cancer among BRCA1 mutation carriers (from 33 to 80%)." (PMID 39863726, 2025). "In the case of patients with a hereditary burden of breast cancer and ovarian cancer (who are carriers of the BRCA1/2 gene mutation), follow-up medical and imaging examinations are recommended." (PMID 40429755, 2025). "This should first be investigated in larger studies before physicians and patients are made aware of this increased risk of malignancies other than breast and ovarian cancer in female BRCA1/2 GPV carriers." (PMID 40427184, 2025). "Breast and ovarian cancers with mutations in the BRCA1 and BRCA2 genes are especially sensitive to PARP inhibitors." (PMID 40647506, 2025). "ESMO recommends that all patients with high-grade ovarian cancer undergo germline and/or somatic BRCA1/2 mutation testing at diagnosis." (PMID 41463165, 2025). "BRCA1 mutations are classically linked to an increased risk of breast and ovarian cancers, but they have also been associated with higher risks for other malignancies, including pancreatic, prostate and, as seen in this case, cervical cancer." (PMID 40949480, 2025). "PARP inhibitors are effective in treating ovarian cancer, especially for BRCA1/2 pathogenic variant carriers and those with HRD (homologous recombination deficiency)." (PMID 40069561, 2025). "In ovarian cancer patients, the mutations in BRCA1/2 and mismatch repair (MMR) genes, as well as homologous recombination deficiency (HRD) status and platinum resistance of the tumor, should be evaluated to predict the treatment response." (PMID 41226862, 2025). "The CSCO emphasizes the detection of BRCA1/2 germline mutations in populations at high risk for breast and ovarian cancer to guide the use of PARP inhibitors." (PMID 41301752, 2025). "Compared to the general population, individuals with BRCA1/2 mutations have a 70% and 40% increased risk of developing breast and ovarian cancer, respectively." (PMID 40424327, 2025). "A systematic review examined the impact of dietary habits, weight changes, and physical activity on the risk of breast and ovarian cancer in women with P/LP variants in BRCA1/BRCA2 P/LP." (PMID 39858629, 2025).
ovarian carcinoma (continued). "Homologous recombination deficiency (HRD) associated with the BRCA1/2 pathogenic variants is present only in 30% of the ovarian cancer tumors, meaning the remaining 70% are attributable to other genes." (PMID 40188947, 2025). "In our study, 20% (113/555) of the breast and ovarian cancer cases were identified as carriers of PVs in associated genes, with major contributions from BRCA1 and BRCA2 genes (12% and 17%, respectively)." (PMID 40065011, 2025). "Nevertheless, methylstat also sensitized ovarian cancer cell lines with a BRCA1-deficient background." (PMID 39915607, 2025). "It is estimated that up to 10% of patients with high‐grade epithelial ovarian cancers have a pathogenic BRCA1/2 tumor mutation, yet their genomic instability scores are consistent with an HRD‐negative tumor." (PMID 40891252, 2025). "For example, while BRCA1-deficient ovarian carcinomas and triple-negative breast carcinomas show a good response to therapy, this appears to be the opposite for BRCA1-deficient non-triple-negative breast carcinomas and lung carcinomas." (PMID 40519304, 2025). "BRCA1 mutation is a well-established risk factor for ovarian cancer and has been linked to a higher incidence of serous tubal intraepithelial carcinoma (STIC)." (PMID 41154374, 2025). "In the pivotal SOLO1 trial, olaparib demonstrated a durable progression-free survival (PFS) benefit beyond the end of treatment in patients with advanced ovarian cancer and BRCA1/2 mutations." (PMID 40075604, 2025). "This study aimed to evaluate the progression-free survival (PFS) benefit from the PARP inhibitor in relation to the location of mutations in BRCA1/BRCA2 in newly diagnosed ovarian cancer." (PMID 40075604, 2025). "Statistics indicate that the risk of breast and ovarian cancer in BRCA1 mutation carriers is 57% and 40%, respectively, whereas the corresponding risks for BRCA2 mutation carriers are 49% and 18%." (PMID 40859871, 2025). "In the prospective ovarian cancer cohort, pathogenic/likely pathogenic BRCA1/2 variants were detected in 24.19% of cases, with BRCA1 alterations more frequent than BRCA2." (PMID 41465396, 2025). "53BP1 regulates DNA damage response (DDR) by preventing excessive DNA end resection, which limits tumor immunogenicity in BRCA1-deficient ovarian cancer." (PMID 39949780, 2025). "For example, CCNE1 amplification/gain, which is a predictive biomarker of PARPi and platinum-based treatment resistance in epithelial ovarian cancers, is mutually exclusive with a pathogenic BRCA1/2 mutation in ovarian cancers." (PMID 39985088, 2025). "In a meta-analysis, cumulative risk of ovarian cancer among BRCA1 and BRCA2 mutation carriers was 39% and 11% respectively, by 70 years of age." (PMID 40894326, 2025). "The majority of BRCA1-related breast and ovarian cancers, including up to 93% of ovarian cancers with BRCA1 mutations, have been linked to LOH events." (PMID 39747660, 2025). "Prostate, pancreatic, breast, and ovarian cancers linked to BRCA1/2 mutations have all been authorized for it." (PMID 40141415, 2025). "In ovarian cancer, particularly among patients harboring BRCA1/2 mutations, inhibition of the BER pathway has been linked to improved outcomes with immunotherapy." (PMID 40647471, 2025). "Women carriers of BRCA1/2 mutations face a very high lifetime risk (penetrance) of developing breast and/or ovarian cancer." (PMID 40782011, 2025). "About 18% of all ovarian cancers are associated with BRCA1/2 variants while another 6% are attributed to variants in other genes." (PMID 39907309, 2025). "Ovarian cancer (OC) is a highly heterogeneous malignancy influenced by germline genetic factors, with BRCA1/2 mutations being well-established risk factors." (PMID 40777133, 2025). "Hereditary ovarian carcinomas demonstrate better NACT outcomes in BRCA2 vs. BRCA1 mutation carriers." (PMID 40547808, 2025).
ovarian carcinoma (continued). "A similar pattern was observed in BRCA1-mutated breast and ovarian cancers, identifying this as a poor prognosis HCC subtype associated with replication stress." (PMID 40546347, 2025). "A large-scale Phase III study, SOLO1, further demonstrated that among 196 patients with BRCA1/2 mutations and platinum-sensitive recurrent ovarian cancer, Olaparib treatment resulted in a PFS of 19.1 months, compared to just 5.5 months in the placebo group." (PMID 40395324, 2025). "Regarding cancer type and gender in pathogenic variants, BRCA1 was more commonly associated with breast and ovarian cancer, while BRCA2 was more widely detected in prostate cancer, pancreatic cancer, cholangiocarcinoma, and others." (PMID 40249378, 2025). "By age 70, women with BRCA1 mutations have a 39% risk of developing ovarian cancer, while those with BRCA2 mutations have an 11% risk." (PMID 41471359, 2025). "Dose response curves were performed with carboplatin and the PARPi olaparib using various prostate cancer lines, plus BRCA1-deficient UWB1.289 ovarian cancer cells as a bona fide HRd control." (PMID 39071291, 2025). "Induced pluripotent stem cells (iPSCs) derived from patients with early-onset ovarian cancer carrying BRCA1 gene mutations possess the capability to differentiate into fallopian tube epithelial (FTE)-like structures." (PMID 40191206, 2025). "Among these, the PARPi Olaparib, approved in 2014 for germline BRCA1/2-mutated ovarian cancer and in 2019 for BRCA1/2-mutated PDAC, was the first agent to directly exploit DNA repair deficiencies in cancers." (PMID 41009605, 2025). "The PALB2 gene is often tested in individuals with a family history of breast or ovarian cancer, especially those with a known BRCA1 or BRCA2 mutation." (PMID 39996890, 2025). "Initially, NBR2 was thought to be co-mutated or deleted alongside BRCA1 in malignancies due to the high mutation/deletion rate of BRCA1 in breast and ovarian cancers." (PMID 39997609, 2025). "Hereditary breast and ovarian cancer (HBOC) syndrome accounts for 5–10% of all breast and ovarian cancers, with BRCA1 and BRCA2 pathogenic variants being the most common genetic alterations." (PMID 41301857, 2025). "These inhibitors have shown efficacy not only in ovarian cancer but also in breast, prostate, and pancreatic cancers, particularly in patients with BRCA1/2 mutations or other defects in DNA repair pathways." (PMID 40299557, 2025). "Risk-reducing salpingo-oophorectomy (RRSO) proves to be an efficacious strategy for mitigating BC and ovarian cancer risk in females harbouring BRCA1/2 germline pathogenic variants, particularly in those of a younger age group." (PMID 40626017, 2025). "Other studies have also reported a significantly reduced risk of developing ovarian cancer among BRCA1 and BRCA2 mutation carriers who had used combined oral contraceptives." (PMID 39863726, 2025). "We used cervical, breast, lung and ovarian cancer cells bearing mutations in BRCA1 or ATM and depleted SETD1A using siRNA or CRISPR/Cas9." (PMID 39994444, 2025). "The predisposition to breast and ovarian cancer is caused by high-penetrance genes, such as BRCA1 and BRCA2, which are associated with a high risk of developing the disease." (PMID 40429755, 2025). "Although the analyses are less extensive than in ovarian cancer, BRCA1/2 mutations are recognized in approximately 5% of USC patients." (PMID 40422510, 2025). "Women with BRCA1 mutations have a 35-70% lifetime risk of ovarian cancer, while BRCA2 mutation carriers have a 10-30% risk." (PMID 40303993, 2025). "Recently, Hosken and Greene have examined anticipatory loss in the context of decision-making among young women who live with BRCA1/2 gene mutations, implicated in the elevated lifetime risk of breast and ovarian cancer." (PMID 40508893, 2025). "Women with pathogenic/likely pathogenic (P/LP) variants in BRCA1/2 genes have an increased lifetime risk of breast and ovarian cancer." (PMID 40445415, 2025).